KRTAP23-1 (keratin associated protein 23-1)
Description:
In the hair cortex, hair keratin intermediate filaments are embedded in an interfilamentous matrix, consisting of hair keratin-associated proteins (KRTAP), which are essential for the formation of a rigid and resistant hair shaft through their extensive disulfide bond cross-linking with abundant cysteine residues of hair keratins. The matrix proteins include the high-sulfur and high-glycine-tyrosine keratins.
Synonyms: KAP23.1
Tractability: No criterion of Open Targets' tractability assessment is met for any kind of drug.
Gene: Protein-coding gene on chromosome 21 (30,348,399 to 30,348,606, reverse strand). Ensembl gene ENSG00000186980.
Pathways (Reactome):
Developmental Biology: Keratinization
Gene Ontology:
Molecular function: protein binding
Cellular component: cytosol
Genetic constraint (gnomAD): Loss-of-function variants: 0 observed, 0.25 expected, observed/expected ratio (o/e) 0, 90% interval 0 to 1.87. That is too few expected variants to judge how well the gene tolerates losing a copy. Missense variants: 70 observed, 77.03 expected, observed/expected ratio (o/e) 0.91, 90% interval 0.75 to 1.11. Synonymous variants: 37 observed, 35.89 expected, observed/expected ratio (o/e) 1.03, 90% interval 0.79 to 1.36.